KISS1 (KiSS-1 metastasis suppressor)
Description:
Kisspeptins are ligands for the G protein-coupled receptor KISS1R/GPR54. The hypothalamic KISS1/KISS1R signaling system plays a central role in the regulation of the hypothalamic-pituitary-gonadal reproductive axis by modulating the secretion of gonadotropin-releasing hormone (GnRH) from GnRH neurons. In these neurons, kisspeptin binding to its receptor activates G(q)-dependent signaling, leading to phospholipase C (PLC) activation, and hydrolysis of phosphatidylinositol 4,5-bisphosphate (PIP2). The subsequent rise in intracellular calcium levels results in the inhibition of inward rectifier potassium channels and activation of TRPC-like cation channels, leading to GnRH neurons depolarization and stimulation (By similarity). In addition to this pathway, kisspeptin also triggers G(q)-independent signaling via beta-arrestin, leading to MAPK cascade activation and ERK1/ERK2 phosphorylation. Kisspeptins are also involved in the regulation of other processes including cell growth, cell proliferation and cell migration. [Kisspeptin-10]: Binds the G protein-coupled receptor KISS1R/GPR54 and triggers G protein-coupled receptor signaling via activation of G(q) and phosphatidylinositol 4,5-bisphosphate (PIP2) hydrolysis by phospholipase C. Binding to the receptor also activates beta-arrestin-dependent signaling resulting in ERK1/2 phosphorylation. Activation of the receptor inhibits cell proliferation and cell migration, and is involved in the regulation of trophoblast invasion during early stages of pregnancy. Is also involved in the modulation of airway smooth muscle cells migration. In bone tissue, activation of KISS1R by kisspeptin-10 recruits phosphatase DUSP18 and SRC to the KISS1R C-terminus through a G(q)-dependent signaling pathway. This leads to DUSP18-mediated dephosphorylation of SRC, down-regulation of osteoclast differentiation and activity, and consequently suppression of bone resorption (By similarity). [Metastin]: Receptor binding triggers G protein-coupled receptor signaling via activation of G(q) and phosphatidylinositol 4,5-bisphosphate (PIP2) hydrolysis by phospholipase C.
Synonyms: HH13; KiSS-1
Tractability: Antibody: its Gene Ontology location is reachable by antibodies, with high confidence; UniProt places it where antibodies can reach, with medium confidence; UniProt predicts a signal peptide or a membrane-spanning region.
Gene: Protein-coding gene on chromosome 1 (204,190,341 to 204,196,491, reverse strand). Ensembl gene ENSG00000170498.
Subcellular location: Secreted
Subcellular location (Human Protein Atlas): Vesicles; Predicted to be secreted
Pathways (Reactome):
Signal Transduction: G alpha (q) signalling events; Peptide ligand-binding receptors
Gene Ontology:
Molecular function: protein binding; kisspeptin receptor binding
Biological process: cytoskeleton organization; G protein-coupled receptor signaling pathway; negative regulation of bone resorption; positive regulation of luteinizing hormone secretion
Cellular component: extracellular region
Genetic constraint (gnomAD): Loss-of-function variants: 0 observed, 1.49 expected, observed/expected ratio (o/e) 0, 90% interval 0 to 1.55. That is too few expected variants to judge how well the gene tolerates losing a copy. Missense variants: 179 observed, 153.43 expected, observed/expected ratio (o/e) 1.17, 90% interval 1.03 to 1.32. Synonymous variants: 96 observed, 77.2 expected, observed/expected ratio (o/e) 1.24, 90% interval 1.05 to 1.47.
Homologues: Orthologues: chimpanzee KISS1 (99% identical), macaque KISS1 (87% identical), guinea pig KISS1 (60% identical), mouse Gm28040 (48% identical), mouse Kiss1 (48% identical), rat Kiss1 (38% identical), tropical clawed frog kiss1 (33% identical), zebrafish kiss1 (20% identical).
Diseases named in the same sentence as KISS1 in open-access papers:
KISS1 is named in the same sentence as 135 diseases in open-access papers, as found by Europe PMC text mining. Sharing a sentence is not in itself a finding about the gene and the disease. The quoted sentences say what the papers report.
melanoma (54 papers, 2007 to 2026). A malignant, usually aggressive tumor composed of atypical, neoplastic melanocytes. "Kisspeptins are proteins encoded by the Kiss1 gene that was initially discovered as a human metastasis suppressor gene in melanoma and several breast cancer cell lines." (PMID 37987885, 2024). "Here, a role for KiSS1 as regulator of the cellular response to vemurafenib in melanoma cell lines all characterized by the BRAF V600E mutation has emerged." (PMID 37790750, 2023). "The loss of KiSS1 in tumor progression/metastases has been associated with other cancer types in addition to melanoma." (PMID 37790750, 2023). "The gene encoding kisspeptin (KISS-1) was first identified in 1996 as a metastasis tumour-suppressor gene in malignant melanoma cell lines and its peptide product was initially termed ‘metastin’." (PMID 35928889, 2022). "In 1996, metastin, encoded by the Kiss1 gene, was found to have the ability to suppress metastatic decrease in melanoma cells." (PMID 36231110, 2022). "The KISS1 gene is the metastasis suppressor gene in melanoma, which maps to chromosome 1q32 and encodes a largely hydrophobic 145-amino-acid protein." (PMID 35117986, 2021). "The Kiss1 gene that encodes the kisspeptin precursor, Kiss1, was discovered in 1996 as a metastasis suppressor in melanoma cell lines, and a few years later, Kiss1R, previously known as GPR54, was discovered." (PMID 34576283, 2021). "In 1996, kisspeptin (the 145 amino acid) and its encoding gene KISS1 were first identified as a suppressor (and a gene) of human malignant melanoma in Hershey, Pennsylvania, USA—the hometown of the famous Hershey’s kisses chocolates." (PMID 29354093, 2017). "KISS1, the gene encoding kisspeptins, was originally identified in 1996 as a suppressor of metastasis in human malignant melanoma." (PMID 24615662, 2014). "C8161.9 melanoma cells were transduced with KISS1 in which K57, R67 and R124 (C1C2C3) were mutated to alanine." (PMID 24454770, 2014). "KISS-1 is a gene which encodes metastin (fragment of KISS-1), and it is expressed primarily in melanoma and breast cancer cells." (PMID 23340652, 2013). "Kisspeptins, encoded by the Kiss1 gene, are peptides derived from a common precursor named kisspeptin-54, which was originally termed metastin by its ability to suppress melanoma metastasis." (PMID 24101924, 2013). "Of note, detection of WNT5A in the RGP library is in marked contrast to previous evidence that WNT5A is strongly associated with aggressiveness in human melanoma and also to a most recent finding that KISS1 expression is down-regulated by Wnt5a." (PMID 18211678, 2008). "Upregulation of the KiSS1 gene, which encodes the protein Kisspeptin, has been associated with inhibition of metastasis and maintenance of dormancy in preclinical models of breast cancer, ovarian cancer, and melanoma." (PMID 34064392, 2021). "Kisspeptin, the KISS1 gene product, was first discovered to be a metastasis suppressor in a screen of human malignant melanoma cells, and soon thereafter, was also found to suppress breast cancer metastases, leading to its initial designation as ‘Metastin’." (PMID 40430029, 2025). "More recently, KiSS-1 has been reported to play a role in modulating the apoptotic response of melanoma cells to antitumor drug exposure, including vemurafenib." (PMID 38732265, 2024). "KiSS1 is a metastasis suppressor originally identified in melanoma cells, known to play an important physiological role in mammals’ development and puberty." (PMID 37790750, 2023). "KiSS1 espression of melanoma cells and the levels of KiSS1 released into the culture medium were measured using ELISA." (PMID 37790750, 2023). "In melanoma, the metastasis suppression properties of KiSS1 have been reported to counteract metastatic colonization and to control the dormancy of disseminated cells following secretion." (PMID 37790750, 2023).
melanoma (continued). "The link between KISS1 and mitochondrial function has been demonstrated in human melanoma cells by Welch and colleagues, whose pioneering work led to the initial discovery of KISS1 as an antimetastasis gene in melanoma cells." (PMID 35349482, 2022). "This study showed that overexpression of KISS1 in human melanoma cells resulted in increased mitochondrial biogenesis and higher oxidation of fatty acids via β-oxidation by inducing AMPK activation." (PMID 35349482, 2022). "In the human melanoma cell, Kiss1 inhibits the acetyl-CoA carboxylase phosphorylation by AMPK directly or upregulates PGC1α mRNA to activate the AMPK expression, which enhances mitochondrial β-oxidation and thus reverses the Warburg effect." (PMID 36231110, 2022). "In 1996, Kiss-1 was already discovered in the melanoma cells, and adolescent rats had considerably higher levels of Kiss-1 mRNA expression." (PMID 36421874, 2022). "These KISS1-mediated metabolic changes were essential for KISS1 to suppress melanoma cell invasion and metastasis." (PMID 35349482, 2022). "In this section, the effect of KISS1 inhibition on melanoma cells' migration was evaluated via a wound‐healing assay." (PMID 34096173, 2021). "The results showed that inhibition of KISS1 increased the migration of melanoma cells compared with the control, while this effect was attenuated when combined with Let‐7i." (PMID 34096173, 2021). "Data obtained from qRT‐PCR showed that the expression of Let‐7i and KISS1 has been down‐regulated in melanoma tissues." (PMID 34096173, 2021). "The KISS1 gene was discovered as a novel metastasis-suppressor in human melanoma cells in 1996 in Hershey, named after the famous chocolate of the city, Hershey’s Kisses." (PMID 33503835, 2021). "In this regard, the present study intended to determine the expression of Let‐7i and KISS1 in patients with melanoma." (PMID 34096173, 2021). "In this regard, a statistically significant reduction in both Let‐7i expression and KISS1 expression was observed in melanoma tissues in comparison with non‐tumour marginal tissues (***P < 0.001, ****P < 0.0001)." (PMID 34096173, 2021). "Since Let‐7i has been thought to be a tumour suppressor microRNA in melanoma, and the participation of KISS1 has been suggested to be important in melanoma carcinogenesis, we aimed to determine their probable correlation in melanoma." (PMID 34096173, 2021). "This study was aimed to determine the role of Let‐7i and KISS1 in melanoma cell migration and proliferation." (PMID 34096173, 2021). "Arab and coworkers found that TCF21 directly bind the promoter of KISS-1 gene, known as metastasis inhibition gene in a number of tissues, to enhance its expression in melanomas." (PMID 35201460, 2021). "The Kiss-1 was first discovered in malignant melanoma cells in 1996, and the expression of Kiss-1 mRNA was significantly increased in pubery rats." (PMID 32831859, 2020). "Kisspeptin1 (Kiss-1) has been identified as a human metastasis-suppressing gene with the ability to suppress the metastasis of certain cancers, such as melanoma and breast cancer." (PMID 32328196, 2020). "KISS1 expression elicits a dormancy state of the disseminated melanoma cells, inducing a suppression of metastatic colonization to multiple organs." (PMID 31336647, 2019). "KISS1 was first discovered in melanoma; subsequently, KISS1 was reported to affect the growth, invasion, and migration of tumor cells and confirmed to be an important tumor suppressor gene in multiple types of malignant tumors." (PMID 31803739, 2019). "KiSS-1 has been described as a gene suppressor of metastasis in melanoma and more recently in other types of cancer, such as breast cancer, CRC, lung, thyroid, bladder, gastric, and other cancers." (PMID 29760678, 2018).
melanoma (continued). "Among the different aggregates that were formed, one involves KISS1, relevant for cytoskeletal reorganization downstream cell matrix adhesion, a gene known to suppress metastases in melanoma and in some breast cancers too, by inhibiting invasion." (PMID 30485296, 2018). "Since the seminal discovery that KISS1 regulates metastasis of melanoma cells, a large and growing body of studies has described roles for KISS1 and KISS1R mRNA and protein in regulating tumor growth and metastasis." (PMID 30123188, 2018). "While KISS1 and KPs are recognized as potent positive regulators of the reproductive neuroendocrine axis in mammals, the first reported role for KISS1 was that of metastasis suppression in melanoma." (PMID 30123188, 2018). "Transfection of KiSS-1 into metastatic human melanoma cell lines suppressed metastasis in athymic nude mice by 50–95%." (PMID 29760678, 2018). "TCF21 expression is downregulated in metastatic melanoma by hypermethylation of a promoter, and overexpression of TCF21 inhibits the motility of melanoma cells via KISS1." (PMID 28476165, 2017). "KISS1 was originally identified as a human metastasis suppressor gene that is able to suppress the metastasis of melanoma and breast cancer." (PMID 29354093, 2017). "The KISS1 gene was originally identified as a potent melanoma metastasis suppressor, where expression levels correlated inversely with the metastatic potential in a panel of melanoma cell lines." (PMID 28207895, 2017). "KISS1 was originally identified as a human metastasis suppressor gene (also named metastin) that had the ability to suppress melanoma and breast cancer metastasis." (PMID 28636637, 2017). "While KISS1 is noted as a tumor suppressor in melanoma metastasis, the role of KISS1R signaling on breast cancer invasion is dependent on the estrogen receptor status of the tumor cells." (PMID 27158817, 2016). "KiSS-1 can inhibit chemotaxis and invasion by attenuating the metastasis of breast cancer and melanomas." (PMID 25810563, 2015). "The KISS1 gene, initially discovered as a novel human malignant melanoma metastasis-suppressor gene, has been validated as an anti-metastatic gene by preclinical and clinical evidence in various types of cancer." (PMID 25846316, 2015). "Kisspeptin-1, encoded by KISS1 gene, on chromosome 1q32, was early identified in 1996 as a suppressor of metastasis in human malignant melanoma." (PMID 25254043, 2014). "KiSS-1 has been demonstrated to act as a suppressor in melanoma, thyroid cancer, bladder cancer, gastric cancer, esophageal cancer, and ovarian cancer." (PMID 19154616, 2009). "In 1996, KiSS-1 was identified as a human metastasis-suppressing gene in melanoma cells and breast cancer cells." (PMID 19154616, 2009). "The KISS1 gene product, the secreted protein kisspeptin/metastin, plays an inhibitory role in chemotaxis and invasion of melanoma cells by a mechanism involving remodeling of the actin cytoskeleton." (PMID 18211678, 2008). "This is concomitant with upregulation of a breast and melanoma metastasis suppressor protein, namely KiSS1 (melanoma metastasis suppressor; metastin)." (PMID 18328103, 2008). "For selecting the cell lines, we checked on the expression of three known molecular markers of melanoma progression, KISS1 and RHOC mRNAs and the αvβ3 integrin, in the panel of melanoma cell lines used here." (PMID 18211678, 2008). "On the other hand, levels of the secreted metastasis-suppressor KiSS1 (melanoma metastasis suppressor) were increased in the secreted proteome of the MRJ(L)-expressing cells." (PMID 18328103, 2008). "Kisspeptins were first discovered through microcell-mediated chromosome transfer experiments that defined the KiSS-1 locus as a suppressor of melanoma tumour metastasis." (PMID 18005407, 2007). "However, KISS1 has been reported to suppress the metastasis of various cancers, such as melanoma, bladder cancer, and lung cancer." (PMID 41523580, 2026).
melanoma (continued). "The KiSS-1 protein inhibits melanoma and breast carcinoma metastasis." (PMID 39336709, 2024). "Indeed, KiSS-1 mRNA levels have been shown to be up-regulated by HDAC and DNMT inhibitors, and KiSS-1 has been proposed to sensitize head and neck squamous cell carcinoma, lung cancer models to cisplatin, and melanoma cells to vemurafenib." (PMID 38732265, 2024). "While kisspeptin was initially shown to suppress metastasis in melanoma, subsequent studies have found that KISS-1/kisspeptin could boost metastasis in malignancies ranging from liver to breast cancer, suggesting a dual identity for kisspeptin in cancer." (PMID 35875143, 2022). "KISS1 has been known as a regulator of metastasis in cancers, such as melanoma." (PMID 34096173, 2021). "KISS1 was first identified as a human melanoma metastasis suppressor gene in 1996." (PMID 34620174, 2021). "KiSS1 was first described as a potential suppressor of melanoma metastatic capability." (PMID 34096173, 2021). "At the final stage, this work was aimed to determine a possible correlation between Let‐7i and KISS1 in melanoma pathogenesis, so KISS1 inhibitor alone and in combination with Let‐7i was transfected and cell migration and proliferation were measured by wound‐healing and MTT assays, respectively." (PMID 34096173, 2021). "In this regard, we hypothesized that KISS1 inhibition could increase melanoma cells' proliferation and its expression may be attenuated after Let‐7i transfection." (PMID 34096173, 2021). "The results revealed that either Let‐7i or KISS1 were down‐regulated in patients with melanoma." (PMID 34096173, 2021). "At first, the expression of Let‐7i and KISS1 was determined in patients with melanoma." (PMID 34096173, 2021). "KISS1 was primarily identified as a human malignant melanoma metastasis-suppressor gene." (PMID 31336647, 2019). "Furthermore, it is demonstrated that treatment with KiSS-1 derived polypeptides reduced metastasis in mice engrafted with melanoma cells with GPR54 over-expression." (PMID 29662466, 2018). "KiSS-1 was first described as a metastasis suppressor gene in malignant melanoma." (PMID 29760678, 2018). "In particular, KISS1 is a gene suppressing melanoma (MEL) and breast cancer (BC) metastasis, and KRT17 shows up-expression that may be related to skin lesions and acts as a promoter of epithelial proliferation by regulating immune response." (PMID 28824643, 2017). "Interestingly, KISS1 was first discovered as a metastasis suppressor gene and thought to play a role in suppression of metastasis of breast cancers and melanomas." (PMID 26056364, 2015). "Kiss-1 has been identified as a putative human metastasis suppressor gene in melanomas." (PMID 25111296, 2014). "Other authors have found an inverse correlation between KiSS1 expression and melanoma progression." (PMID 22481931, 2012). "KiSS-1 was identified as a metastasis-suppressing gene in melanoma cells." (PMID 19154616, 2009). "Moreover, it could regulate the important target genes involved in melanoma carcinogenesis, one of which (KISS1) was identified for the first time in the literature." (PMID 34096173, 2021). "Besides, it was determined that restoration of Let‐7i could reduce melanoma cells' proliferation and migration by up‐regulating KISS1." (PMID 34096173, 2021). "Thus, they concluded that KISS1 suppresses the metastatic potential of malignant melanoma cell." (PMID 30123188, 2018). "Also, it is tempting to speculate that MRJ(L) may play a similar role in regulating melanoma metastasis by upregulation of KiSS1." (PMID 18328103, 2008). "The role of KISS1/KISS1R signaling is yet unclear in cancer, though it has been proposed to suppress cancer metastasis, such as melanoma, gastric cancer, breast cancer and pancreatic." (PMID 35117986, 2021). "In a melanoma cell line (C8161), re‐expression of TCF21 was described to activate expression of the metastatic suppressor KISS1 and consequently inhibit motility of the cells." (PMID 29080283, 2018).